TF (transferrin)
Diseases named in the same sentence as TF in open-access papers (continued):
Sharing a sentence is not in itself a finding about the gene and the disease.
cancer (continued). "It has been shown previously that cell surface-associated galectin-3 acts as a cell adhesion molecule and increases cancer cell homotypic aggregation by interaction with TF antigen expressed by unknown cell surface molecules on adjacent cells under anchorage independent conditions." (PMID 20565834, 2010). "Proteolysis-inducing factor has also been shown to activate NF-κB in primary hepatocytes and the human cancer cell line HepG2, resulting in the increased production of interleukin-6 and -8 (IL-6 and IL-8) and C-reactive protein and the decreased production of transferrin." (PMID 15714207, 2005). "As cancer cells secrete exosomes aggressively to promote tumor microenvironment (TME) activities, they can also improve exosome uptake by overexpressing of transferrin which is an essential cargo during internalization through clathrin-mediated endocytosis." (PMID 41142789, 2025). "Antisense transcripts of TF genes such as SOX9 and WT1 have been shown to have functional roles in cancer." (PMID 41255714, 2025). "Strategies aimed at inhibiting CD71-mediated iron uptake include the use of transferrin-conjugated cytotoxic agents, monoclonal antibodies targeting CD71, and iron chelators designed to deprive cancer cells of iron." (PMID 41375568, 2025). "By conjugating transferrin (Tf) tothe MSNP surface, the system actively targets cancer cells via transferrinreceptor (TfR)-mediated endocytosis." (PMID 40548610, 2025). "The antagonistic role of RHOB and ABCA7 in cancer reveals that there are complex interactions among Hub-EGFR.Sig, which was also confirmed in our subsequent miRNA–mRNA and TF-mRNA interactive network analysis." (PMID 40574864, 2025). "As mentioned in the Introduction, “total TF” was recently implicated in the development of resistance to KRAS-G12C inhibitors; as such, asTF-targeting via hRabMab1 may hold future promise in tackling this phenomenon in PDAC and other cancers driven by mutant KRAS." (PMID 38473827, 2024). "Here we present the results of meta-analysis studies that assessed the association between specific blood iron markers (total iron, transferrin, transferrin saturation (TSAT), total iron-binding capacity, and ferritin) and different cancer types." (PMID 39246326, 2024). "Another TF, NFATC4, has been reported to be aberrantly activated and is involved in initiation, proliferation, invasion, and metastasis in several types of cancer." (PMID 39273015, 2024). "TF, fVII, intercellular adhesion molecule-1 (ICAM-1), and multiple pro-inflammatory cytokines can be induced in response to hypoxia in EOC cancer cells at the gene expression level, leading to the autonomous production of the TF–fVII complex." (PMID 39149564, 2024). "The TF-FVIIa complex can activate the PAR2 signaling pathway, leading to increase VEGF expression that promotes cancer progression." (PMID 37386391, 2023). "This suggests that three Hub TF genes are upregulated in TNBC cells, and their downstream target genes will affect the positive regulation of functions related to cancer cell proliferation." (PMID 37686305, 2023). "We investigated the single nucleotide variations (SNVs) of HFRS genes in different cancers and observed that some genes (CCT6A, TF, KRT14, P4HA2, PGK1, SLC16A2, and STC2) were frequently mutated in COAD, STAD, UCEC, and SKCM." (PMID 36998462, 2023). "As one of the largest TF families, the KLF family has been reported to be engaged in cancer progression in cancers of various origins." (PMID 37400979, 2023). "A system of tripterine modified with both transferrin and cell-penetrating peptide SA-R6H4 (Tf/SA-R6H4-TBG-MEs) for combinational and tumor-targeted cancer therapy was investigated." (PMID 37514175, 2023). "TF/VIIa facilitates PAR-1- and PAR-2-mediated signaling responsible for the proliferative response of cancer cells." (PMID 37046617, 2023).
cancer (continued). "Generally, iron is internalized by endocytosis via the TF/TFR system of cells, and cancer cells can maintain a cellular iron balance by regulating the TF/TFR system." (PMID 36139668, 2022). "After being modified by the phosphorylation, the activated TF JDP2 would upregulate the DNA-methylated target gene IL6, which leads to promoting cell apoptosis and immune response against cancer." (PMID 35743172, 2022). "The crystal structure of AAL complexed with Thomsen–Friedenreich (TF), a cancer cell proliferation regulator, provides insight into the interaction of a dimerized AAL with TF through a conservative structural motif-based hydrogen bond network." (PMID 36613681, 2022). "In a similar case, the transferrin (Tf)-conjugated SeNPs exhibited the Tf-guided selectivity between cancer and normal cells due to the high expression levels of TfR in MCF-7 cancer cells." (PMID 36290687, 2022). "Results show that SPARCL1, CDH2, CP, HP, TF and SERPINA5 were all significant downregulated in cancer tissues (p < 0.05)." (PMID 34422629, 2021). "Tumor-cell derived tissue factor (TF, also known as Factor III) contributes to the coagulopathy in cancer to a great extent." (PMID 34433454, 2021). "Subsequently, the decreased binding capacity at acidic conditions in endosomes leads to the dissociation of DHA and iron from transferrin, which activates DHA to form ROS in cancer cells." (PMID 35047402, 2021). "By conjugating DOX with transferrin (DOX–Tf conjugate), we proposed that Tf-bound DOX would improve drug cytotoxicity toward human cancer cells and that normal cells would remain intact." (PMID 33321722, 2020). "The MUC1‐related Tn, TF, STn, and STF TACAs, expressed in more than 90% of primary adenocarcinomas, are considered pancarcinoma antigens and have been widely used to design cancer vaccines." (PMID 32594569, 2020). "Since leukemia cells overexpress transferrin (Tf) receptors on their surface, we proposed doxorubicin–transferrin (DOX–Tf) conjugate as a new vehicle to increase drug concentration directly in cancer cells." (PMID 33321722, 2020). "The protein capping and the drug release strategy were also studied for “transferrin-capped MSNs (DOX@MSNs-S-S-Tf), which showed cancer-targeting effects and released DOX through uncapping transferrin because of disulfide link destabilization." (PMID 33392264, 2020). "We calculated and plotted the Pearson correlation coefficient r, between the expression of TF genes and the expression of CDH1 or VIM, across 1038 CCLE microarrays for cancer cell lines representing various degrees of E and M states." (PMID 31019211, 2019). "Cytotoxicity on the three cancer cell lines, including AGS, HT-29, and PANC-1, revealed that TF-AuNPs were more cytotoxic than TF-AgNPs." (PMID 31151313, 2019). "However, it has never been reported whether injecting transferrin into cancer-bearing hosts causes cancer cells to increase transferrin uptake." (PMID 30202000, 2018). "Targeted iron chelation cancer therapy and NIR imaging were demonstrated effectively in vitro with NNE3TA-Transferrin-Cy5.5." (PMID 29755355, 2018). "For example, a simple, effective and safe self-assembly strategy was developed to fabricate transferrin NPs with NIR dye IR780 (Transferrin-IR780 NPs) for targeted imaging and phototherapy of cancer." (PMID 29755355, 2018). "NONHSAT102729 and NONHSAT078790 were the core lncRNAs in TF-lncRNA network (n335563 and n340532 respectively), and XIST has been extensively studied in other cancers and it is also downregulated in DLBCL cell lines to certain extent." (PMID 28423571, 2017). "Therefore, this phenomenon can introduce cerium as a candidate to inhibit cancer cell proliferation and the effectiveness of cerium in the presence of transferrin showed that this element may have a similar mechanism of endocytosis mediated by transferrin receptor." (PMID 26664465, 2015).
cancer (continued). "In line with TF, also antibodies against Tn seemed to have therapeutical meanings: a monoclonal antibody to Tn (2154F12A4) selectively recognized Tn and inhibited the adhesion of cancer cells to the lymphatic endothelium, and could thus inhibit lymphatic metastases." (PMID 26528431, 2015). "It is therefore important, especially in the case of cancer, to increase the amount of PPIX in the blood, and follow this we have amount of HSA-PPIX and also (HSA-PPIX)-TF complex." (PMID 24392106, 2014). "We have three NAF biomarkers (TF, uPA and PAI-1) which together appear highly predictive of the presence of cancer or precancer in women requiring breast biopsy to exclude disease." (PMID 22296682, 2012). "Among them, galectin-3-binding protein and ALDH1A1 were found preferentially elevated in TNBC, whereas CK19, transferrin, transketolase, and thymosin β4 and β10 were elevated in HER2-positive cancers." (PMID 22110952, 2011). "Here we can compare how cancer cells may up-regulate exosome secretion by enhancing RAB regulatory factors and they also enhance exosome uptake by target cells via transferrin overexpression to ensure the seamless transfer of CDE cargo." (PMID 41142789, 2025). "While current literature does not specify which state cancer cells are “addicted” to, ferric iron is insoluble and is often coupled to protein chaperones (e.g., transferrin) for its transport." (PMID 39201626, 2024). "Similar to serum iron, transferrin saturation appears to affect cardiovascular disease-specific but not cancer-specific mortality." (PMID 39464186, 2024). "Another multivariate test used in the diagnosis of OC to evaluate the risk index for malignancy is the OVA1 assay, which is composed of five cancer-related proteins: CA125, ApoA-1 (apolipoprotein A-1), TTR (transthyretin), TF (transferrin), and β2-microglobulin." (PMID 38732363, 2024). "The anti-cancer effects of DFO are not mediated by prevention of iron uptake by transferrin but rather by an intracellular pool of iron that is necessary for DNA synthesis." (PMID 39262774, 2024). "The transferrin dipstick appears to be a highly sensitive test for detecting not just cancer but also precancerous lesions, providing an additional tool for CRC screening with an overall accuracy of 76.4% for detecting CRC and precancerous lesions." (PMID 39113707, 2024). "For example, excess iron release causing increased transferrin saturation and formation of non-transferrin-bound-iron (NTBI) has been observed from tissue damage in iron overloading conditions and during cancer chemotherapy and radiotherapy treatments." (PMID 37629109, 2023). "Transferrin (TF) and transferrin receptor (TFR) bind to form a complex that is involved in intracellular iron transport and is the main pathway for iron uptake by cancer cells, which was found to be essential for the induction of cellular ferroptosis by glutamine depletion assays." (PMID 37818101, 2023). "Moreover, we found that TPD52, TF, and CCT6A were more frequently heterozygous amplified while STC2, CISD1, and P4HA2 were more likely to occur in heterozygous deletion in cancers." (PMID 36998462, 2023). "On the one hand, studies revealing an impact of IDH1 mutation on VTE suggested that this genetic event may drive methylation-mediated down regulation of two procoagulant effectors, TF and PDPN in cancer cells." (PMID 38188342, 2023). "TEAD1 is a key TF in various oncogenic signaling pathways, including the Hippo, Wnt, TGFβ, and EGFR pathways, and plays critical roles in EMT, metastasis, drug resistance, and cancer stem cells." (PMID 35999456, 2022). "The TF-gene and ceRNA network suggests that three hub genes may act as a bridge between CAD and cancer, which of course requires further experimental studies." (PMID 35799780, 2022).
cancer (continued). "Increases in serum ferritin, serum iron, transferrin iron saturation, hemosiderin deposition in macrophages and similar changes in cancer patients are negative prognostic features in the progress of the disease." (PMID 36430469, 2022). "Circulating iron is complexed in TF; then, TF binds to the TFR in the surface of cancer cells." (PMID 36139668, 2022). "NPs can be localized to specific brain tissues by designing ligands that can attach both to receptors on the apical surface of BBB endothelial cells and target tissue, including the transferrin and low-density lipoprotein receptors, which are found at the BBB and are over-expressed in cancer cells." (PMID 35456971, 2022). "Then, through the signaling transmission of cascade proteins DNAH14 and CPSF4, it could enter the nucleus to downregulate TF MED17, resulting in an androgen-dependent reduction of cancer cells." (PMID 35164166, 2022). "The anticancer activities of Rubia cordifolia and its constituents have been reported earlier, but their influence on the crosstalk of complex cancer-related signaling metabolic pathways (i.e., transcription factors; TF) has not yet been fully investigated." (PMID 33572569, 2021). "EV TF activity, PAI-1 (threefold median increase), TAT (12-fold median increase), and D-dimer (sevenfold median increase), were all elevated in patients with terminal cancer compared to healthy individuals." (PMID 33658563, 2021). "TFRC is a cell surface receptor that is responsible for transferrin‐mediated iron uptake; thus, TFRC may play a key role in the energy supply of cancer cells." (PMID 33626208, 2021). "LINC-ROR stimulates cancer stem cell phenotype and ESCC progression through the deregulation of SOX9, as a TF involved in embryogenesis and maintenance of stem/progenitor cells, to coordinately promote cell proliferation, motility, self-renewal capacity, and cancer stemness state." (PMID 33745265, 2021). "The most significantly enriched TF gene was GRHL2, known as an EMT suppressor in various cancers." (PMID 34356119, 2021). "Human serum transferrin (HST) is a glycoprotein involved in iron transport that may be a candidate for functionalized nanoparticles to bind and target cancer cells." (PMID 34210014, 2021). "Here, we developed a hybrid thermosensitive nanoparticle (TMNP) which could co-deliver paclitaxel-loaded transferrin (PTX@TF) and marimastat-loaded thermosensitive liposomes (MMST/LTSLs) for the dual targeting of cancer cells and the microenvironment." (PMID 34959271, 2021). "We previously reported that transferrin is expressed by neutrophils, but not cancer cells, in the metastatic microenvironment and that it mediates neutrophil-dependent mitogenic effects on cancer cells." (PMID 33679721, 2020). "Transferrin (Tf) has demonstrated specific and efficient identification of Tf-receptors in cancer cells irrespective of EMT status." (PMID 32561829, 2020). "The failure of the TF neutralizing antibody to inhibit cancer cell–induced NET formation suggests that the surface TF of cancer cells does not play a role in NET formation, at least under our in vitro conditions." (PMID 31034495, 2019). "In this analysis the mean transferrin saturation and iron level were higher in men who died of cancer over the study than man who did not die of cancer (32.3% vs. 30.08, p = 0.025 and 110.9μg/dl vs. 106.2 μg/dl, p = 0.03, respectively)." (PMID 30640897, 2019). "The high frequency of missing values for some variables considered into the study (namely: transferrin saturation for CKD, as well as ferritin and vitamin B12 for cancer) precluded the possibility to test the independent effect of these risk factors on the study outcome." (PMID 31521117, 2019). "A conjugate of transferrin, NIR dye Cy5.5 and cytotoxic chelating agent (NNE3TA:2,2′-(7-(2-((carboxymethyl)(4-nitrobenzyl)amino)ethyl)-1,4,7-triazonane-1,4-diyl)diacetic acid) (NNE3TA-Transferrin-Cy5.5) was developed to treat and detect cancers." (PMID 29755355, 2018).
cancer (continued). "A transferrin conjugated theranostic micelles of D-alpha-tocopheryl PEG 1000 succinate (TPGS) were synthesized, containing both ultra-bright gold clusters as a model imaging agent and docetaxel as anticancer drug for synchronous cancer imaging and therapy." (PMID 29755355, 2018). "TF antigen is a well-known cancer cell marker saccharide that has galactose at the non-reducing end, like Gb3, but the MytiLec structure shows that it is unlikely to bind." (PMID 27321048, 2016). "As the hypoxic response and regulation of iron metabolism are tightly interconnected, HIF1A may be involved in regulating genes that maintain iron homeostasis, e.g., transferrin, TFR1, ceruloplasmin, and heme oxygenase 1 in cancer." (PMID 26560875, 2016). "We identified six genes including UNG, FUCA2, DERA, GMFB, TF, and SNX24 as significantly downregulated and two genes including MYL9 and TAGLN as significantly upregulated upon mir-145 over-expression in distinct cancer types." (PMID 27655328, 2016). "On the other hand, iron is an essential nutrient for cancer cell proliferation, and iron (Fe(III))-loaded transferrin is transported into cells by binding to the transferrin receptor on the cell surface and the induction of clathrin-mediated transferrin endocytosis." (PMID 26036864, 2015). "Persons with a normal iron intake did not have higher cancer rates, even when their transferrin saturation level was high." (PMID 24152754, 2013). "Clearly, the cancer process is more complex than inflammation alone, and as iron appears to play a role(s) in cancer biology, it is possible that the increase in transferrin concentration observed in the serum of CRC patients is not an acute phase response." (PMID 16755300, 2006). "The randomised phase II Microtec Study evaluated the cumulative incidence of VTE in advanced cancer with lower levels of tissue factor EVs not on thromboprophylaxis enoxaparin (LMWH) compared to patients with higher tissue factor EVs (TF‐EVs) randomised to enoxaparin or observation." (PMID 40292918, 2025). "Since ferritin may be elevated in cancer patients and is not a reliable parameter of iron status, serum transferrin saturation should be determined." (PMID 38240843, 2024). "Systemic manipulation of iron availability through non-toxic chelators could increase transferrin uptake by cancer cells, boosting the efficacy of targeted therapies." (PMID 38117806, 2023). "The unphosphorylated state of TF STAT1 enduring upregulation is responsible for the promotion of cancer growth and metastasis, and the deterioration of the immune response, leading to drug resistance and forcing cancer cells to invade and migrate to other organs in advanced PCa." (PMID 35164166, 2022). "For neutrophils, the immature low-density neutrophils (iLDNs) mobilized by cancer cell-derived granulocyte colony stimulating factor (G-CSF) can promote BCLM, and the liver metastatic growth may be facilitated by neutrophil-derived transferrin in BC." (PMID 36387238, 2022). "Moreover, with the low expression of TF RBMX, it could upregulate miRNA MIR222 for the purpose of downregulating the downstream target genes DIRAS3 and DCTN6, enhancing cancer cell proliferation, cell survival rate, and inducing invasion." (PMID 35164166, 2022). "In fact, transferrin did not affect the temperature elevations in the heart and liver in radiofrequency hyperthermia while boosted dramatically temperature elevations in the cancer tissue." (PMID 30202000, 2018). "Macrophages, cancer cell and T-lymphocytes uptake and reserve non-transferrin bound iron (NTBI) through non-transferrin-bound iron transporters such as ZIP14 and DMT1, functioning as circulating iron isoforms to avoid different tissues from iron-induced cytotoxicity." (PMID 30591630, 2018). "The examples from the previous paragraph might lead one to suspect that the separation we are seeing is driven not by cancer type but by baseline differences in TF expression in the tissues where the cancers originate." (PMID 30305013, 2018).